NUCB2 (nucleobindin 2)
Diseases named in the same sentence as NUCB2 in open-access papers (continued):
Sharing a sentence is not in itself a finding about the gene and the disease.
kidney cancer (1 paper, 2025). Primary or metastatic malignant neoplasm involving the kidney. "In addition, nesfatin-1 and NUCB2 knockout in the kidney cancer cell line resulted in inhibition of proliferation and metastasizing." (PMID 39480586, 2025).
leukemia (1 paper, 2023). A malignant (clonal) hematologic disorder, involving hematopoietic stem cells and characterized by the presence of primitive or atypical myeloid or lymphoid cells in the bone marrow and the blood. "These splicing perturbations alter the composition of numerous hematopoietic stem and progenitor (KLF2, GATA2, GATA1, SPINK2) or leukemia (LAT2 and NUCB2) regulatory factors." (PMID 36697445, 2023).
liver cancer (1 paper, 2024). An epithelial or non-epithelial malignant neoplasm that arises from the liver. "We then investigated the biological function of NUCB2 in liver cancer cells using two independent shRNAs to knock down NUCB2 in SNU449 and Huh7 cells." (PMID 39309426, 2024). "Initially, the expression levels of NUCB2 in tumors from different tissues were investigated to elucidate its function in liver cancer, and NUCB2 was increased in liver cancer." (PMID 39309426, 2024).
oral cancer (1 paper, 2026). "We examined the association of four NUCB2 gene polymorphisms (rs1330, rs214101, rs757081, and rs10766383) and clinicopathological characteristics with oral cancer in Taiwanese men compared with healthy controls." (PMID 41938502, 2026). "Our findings suggest that NUCB2 SNPs may play a pivotal role in oral cancer progression and metastatic potential, particularly in older patients." (PMID 41938502, 2026). "The connections among lifestyle factors that promote cancer, NUCB2 polymorphisms, and oral cancer are still not well understood." (PMID 41938502, 2026).
osteosarcoma (1 paper, 2024). A usually aggressive malignant bone-forming mesenchymal neoplasm, predominantly affecting adolescents and young adults. "Recently, it was found that NUCB2 enhanced osteosarcoma immune escape by elevating CXCL8 expression." (PMID 39309426, 2024).
ovarian dysfunction (1 paper, 2019). The inability of the ovaries to function. "But there have been no reports as to whether the presence of NUCB2/Nesfatin-1 in FF and NUCB2/Nesfatin-1 in blood is related to the pathophysiology of PCOS or ovarian dysfunction in PCOS patients." (PMID 31897389, 2019).
pancreatic cancer (1 paper, 2021). "Due to the difficulties in obtaining pancreatic cancer tissue for research, cell lines may be useful as a model to indicate the role of NUCB2 in this cancer type." (PMID 34361082, 2021). "There are still different types of cancer (e.g., pancreatic cancer) that have not been analyzed in the context of NUCB2 expression." (PMID 34361082, 2021).
retinoblastoma (1 paper, 2022). A malignant tumor that originates in the nuclear layer of the retina. "TSTD1, CDKN2C, NUCB2, and KATNAL1 showed the most significant MYCNARB1PRO-specific downregulated expression pattern among the hypermethylated genes in this retinoblastoma subtype." (PMID 36245757, 2022).
rhinitis (1 paper, 2023). An inflammation of the mucous membrane lining the nose, usually associated with nasal discharge. "The Western blot and immunofluorescent staining results demonstrated that the level of NUCB-2 in tumor tissues was higher than that in rhinitis." (PMID 37635259, 2023). "NUCB-2 level in NPC tissue was higher than that in rhinitis tissue (P < 0.05)." (PMID 37635259, 2023). "Firstly, expression of NUCB-2 was determined in the lesion sites of 39 patients initially diagnosed with NPC and 31 patients with rhinitis." (PMID 37635259, 2023). "An elevated serum level of NUCB-2 in NPC patients was detected, compared to that in patients with other head and neck tumors, rhinitis or healthy donors." (PMID 37635259, 2023).
tendinopathy (1 paper, 2020). "Our study first demonstrated that the NUCB2 levels in tendon tissues from tendinopathy patients were increased when compared with those from healthy controls." (PMID 33344440, 2020). "The results showed that the NUCB2 levels were higher in tendinopathy patients than in healthy controls." (PMID 33344440, 2020).
urothelial carcinoma of the bladder (1 paper, 2020). "This study aimed to examine the clinical significance of NUCB2 expression urothelial carcinoma of the bladder (UCB)." (PMID 32221080, 2020).
tumor (29 papers, 2002 to 2025). "In the present study, the expression of NUCB-2 in NPC tissues associated with the pathological aggression traits of the tumor." (PMID 37635259, 2023). "The analysis of a five-year survival rate indicated that high NUCB2 expression (IRS ≥ 6) in tumor cells was associated with longer patient survival (p = 0.0186, Mantel-Cox test)." (PMID 36012443, 2022). "The analysis of the five-year survival rate indicated that a positive NUCB2/NESF-1 expression in tumor cells was also associated with longer patient survival." (PMID 36012443, 2022). "In clear-cell renal cell carcinoma (ccRCC), the high level of Nucb2 expression was linked to a progressed tumor stage and metastasis." (PMID 34073612, 2021). "The expression of NUCB2/NESF-1 was significantly associated with the tumor depth, lymph node metastasis, lymphatic invasion, venous invasion, and clinical stage." (PMID 34361082, 2021). "Compared with control cells, the loss of KLF4 decreased tumour growth and increased cell apoptosis; however, the phenotypes were reversed by NUCB2 overexpression." (PMID 30055641, 2018). "Recently, the expression of NUCB2/NESF-1 has been linked to tumor development." (PMID 36012443, 2022). "Moreover, a high expression of NUCB2/nesfatin‐1 in GC tissues is significantly associated with tumour depth, lymph node metastasis, lymphatic invasion, venous invasion and clinical stage." (PMID 36065769, 2022). "Recently, the function of NUCB2/NESF1 has been linked to tumor development and metastasis." (PMID 36012443, 2022). "Recently, the expression of NUCB2/NESF-1 has been linked to tumor development and metastasis." (PMID 34361082, 2021). "Recently, the function of nesfatin-1/NUCB-2 is linked to tumor development and metastasis." (PMID 27150059, 2016). "Therefore, we conclude that the expression of NUCB-2 in tumor tissue and nesfatin-1 in serum may have the potential to serve as risk factors for NPC progression." (PMID 37635259, 2023). "This apparent contradiction likely reflects complex immunoregulatory cascades whereby NUCB2‐expressing tumour cells secrete immunomodulatory factors that initially promote T‐cell activation but subsequently induce exhaustion phenotypes." (PMID 40913484, 2025). "Detailed expression profiling demonstrated that NUCB2 was expressed in 74.5% of central tumour cells compared to only 50.9% in peripheral cells." (PMID 40913484, 2025). "Our analyses revealed substantial transcriptomic divergence between anatomically distinct tumour regions, with NUCB2 emerging as significantly upregulated in centre‐residing neural progenitor cell‐like (NPC‐like) tumour cells." (PMID 40913484, 2025). "Through functional validation and correlative analyses, we reveal a previously unrecognised function of NUCB2 in driving GBM aggressiveness through parallel regulation of intrinsic tumour growth and extrinsic immune evasion mechanisms." (PMID 40913484, 2025). "Future studies utilising stable knockout models in conjunction with advanced co‐culture systems or orthotopic tumour models are anticipated to yield unprecedented insights into the temporal regulatory dynamics of NUCB2." (PMID 40913484, 2025). "Future research directions should focus on exploring the precise molecular mechanisms by which NUCB2 modulates both tumour cell‐intrinsic properties and the broader tumour microenvironment." (PMID 40913484, 2025). "Our findings uncover NUCB2 as an important differentially expressed gene (DEG) in central NPC‐like tumour cells and reveal its dual functionality in both promoting tumour cell proliferation and modulating the local immune microenvironment." (PMID 40913484, 2025). "This spatial variation in NUCB2 expression is correlated with distinct tumour microenvironmental characteristics that collectively contribute to the well‐documented therapeutic resistance observed in GBM." (PMID 40913484, 2025).
tumor (continued). "This previously uncharacterised NUCB2‐driven axis represents a promising therapeutic target, potentially enabling simultaneous targeting of tumour cell proliferation and immune evasion mechanisms in this aggressive malignancy." (PMID 40913484, 2025). "This prognostic relevance, combined with the involvement of NUCB2 in both tumour cell proliferation and immune regulation, underscores its potential as a promising therapeutic capable of eliciting multifaceted effects." (PMID 40913484, 2025). "NUCB2-dependent inhibition of senescence in GC engenders aggressive tumor behavior by modulating proliferation, apoptosis, and migration." (PMID 38760405, 2024). "Multivariate Cox regression analysis also showed that NUCB2 IHC score and tumor venous invasion were independent prognostic factors for PFS but not OS." (PMID 38760405, 2024). "NUCB2 expression has a significant impact in GC19,20, but little is known about the exact mechanism(s) by which NUCB2 contributes to tumor progression." (PMID 38760405, 2024). "This new activity of NUCB2 plays a significant role in aggressive tumor progression via the modulation of several other GC cellular phenotypes." (PMID 38760405, 2024). "On day 21 after tumor implantation, the intracranial tumors were removed, and immunohistochemical staining for NUCB2 expression was performed." (PMID 37830634, 2023). "In this study, we assessed the impact of NUCB2 expression on tumor progression and prognosis of GBM." (PMID 37830634, 2023). "The results demonstrate that knockdown of NUCB2 reduces tumor progression and prolongs survival in the mouse model." (PMID 37830634, 2023). "In order to address this issue, we examined the expression levels of NUCB-2 both in serum and tumor tissue from NPC patients." (PMID 37635259, 2023). "In this study, we firstly demonstrated that the expression of NUCB-2 in tumor regions was higher than that in non-tumor sites." (PMID 37635259, 2023). "Knockdown of NUCB2 inhibits tumor proliferation and neovascularization, and enhances the sensitivity of GBM to TMZ and radiation therapy." (PMID 37830634, 2023). "The level of NUCB2 expression in the cytoplasm of IDC cells decreased with the increasing degree of tumor malignancy (G)." (PMID 36012443, 2022). "The findings indicated that the NUCB2/NESF-1 ablation group’s tumor volume was significantly smaller than the control." (PMID 34361082, 2021). "Patients with strong Nucb2 tumor expression had a shorter overall survival rate and increased incidence of recurrence." (PMID 34073612, 2021). "The immunofluorescence analysis showed that the expression of NUCB2/NESF-1 was higher compared to non-tumor regions." (PMID 34361082, 2021). "The results demonstrated that NUCB2/NESF-1 was significantly associated with extrathyroidal extension, TNM stage, and tumor size (p < 0.05)." (PMID 34361082, 2021). "Univariate analysis was carried out with the use of a Cox proportional hazard model from which the tumor grade, T stage, tumor size, NUCB2 expression, and tumor number were identified as significant prognostic factors predicting recurrence-free survival." (PMID 32221080, 2020). "High expression of NUCB2 appeared relevant to aggressive clinicopathological features such as tumor grade (P < .001), TNM stage (P < .001), tumor size (P < .001), and tumor number (P = .005)." (PMID 32221080, 2020). "It is noteworthy that tumor necrosis binding pathway was dysregulated with differentially expressed genes Tnfsf13, Erap1, Tnfsf10, and Nucb2 (p < 0.05)." (PMID 31888290, 2019). "Tumor size, pT stage, Fuhrman grade, necrosis and NUCB2 expression level were included to build nomogram." (PMID 27806328, 2017). "Tumor necrosis, Fuhrman grade and NUCB2 expression level was identified as independent prognostic factors." (PMID 27806328, 2017). "Recently, a few studies revealed the correlation between NUCB2 and tumor development and possible mechanism." (PMID 27806328, 2017).
tumor (continued). "Taken together, NUCB2 shows some characteristics of tumour suppressor gene but further studies investigating the functional significance of the 3-nucleotide deletion and downregulation of NUCB2 expression are required." (PMID 12087473, 2002). "It will also be of interest to elucidate the possible role of NUCB2 in tumour progression and the functional significance of the peculiar three-nucleotide polymorphysm." (PMID 12087473, 2002). "Therapeutic strategies aimed at inhibiting NUCB2 may simultaneously suppress tumour growth and enhance anti‐tumour immune responses, representing a particularly compelling approach for addressing the therapeutic challenges posed by GBM." (PMID 40913484, 2025). "This apparent paradox prompted us to further examine whether NUCB2 might contribute to an immunosuppressive tumour microenvironment." (PMID 40913484, 2025). "Utilising integrative analysis of public single‐cell transcriptomic datasets, we reveal that NUCB2 is markedly upregulated in NPC‐like tumour cells located within the central regions of GBM compared to peripheral areas, suggesting a region specific set of molecular programmes." (PMID 40913484, 2025). "Tumour heterogeneity remains a critical challenge for the efficacy of NUCB2‐targeted interventions." (PMID 40913484, 2025). "Elevated NUCB2 promotes tumor progress in vitro and in vivo." (PMID 39309426, 2024). "The role of NUCB2 in tumor development and metastasis is Janus-like." (PMID 38760405, 2024). "Using IPA software, we found that cholesterol synthesis could be the primary pathway related to NUCB2, and we demonstrated that NUCB2/Nesfatin-1 upregulates cholesterol biosynthesis, promoting tumor invasion and metastasis." (PMID 37277807, 2023). "Interestingly, more and more studies have shown that NUCB2 is an oncogene that improves tumor invasion and metastasis." (PMID 37277807, 2023). "Additionally, NUCB2 not only contributes to tumor progression but also influences the sensitivity of GBM cells to chemotherapy and radiotherapy." (PMID 37830634, 2023). "Interestingly, NUCB2 plays a contrasting role in human adrenocortical and ovarian epithelial carcinoma by inhibiting tumor proliferation and promoting apoptosis." (PMID 37830634, 2023). "Our results indicate that NUCB-2 overexpression in tumor may lead to the elevation of NUCB-2-derived-nesfatin-1 in serum and further tumor progression via systematical regulation of the relative signaling pathways." (PMID 37635259, 2023). "Therefore, the ability of NUCB2/nesfatin‐1 to regulate tumour metastasis and invasion was investigated in the present study." (PMID 36065769, 2022). "Several studies have explored the expression of NUCB2/nesfatin‐1 in various tumours." (PMID 36065769, 2022). "Therefore, NUCB2/NESF1 has become an interesting target for studies in the context of tumor transformation and progression." (PMID 36012443, 2022). "Interestingly, using a mouse model it was found that when circ-001504 was silenced, tumor growth was suppressed, through a mechanism involving NUCB2 downregulation." (PMID 35813211, 2022). "Moreover, positive correlations were found between NUCB2/nesfatin‐1 expression in GC tissues and the tumour depth, lymph node metastasis, lymphatic invasion, venous invasion and clinical stage." (PMID 36065769, 2022). "Taken together, the phenomenon of upregulated expression in various tumour tissues suggests that NUCB2/nesfatin‐1 may play a common role in the occurrence and development of tumours." (PMID 36065769, 2022). "The tumor-bearing group of mice had an increased level of Nucb2 mRNA in the paraventricular nucleus (PVN) compared with the control group, whereas in the arcuate nucleus and brainstem, the expression level of Nucb2 mRNA was similar to that of the control group." (PMID 34073612, 2021). "Also, only tumor grade, T stage, and NUCB2 expression were identified as independent prognostic factors predicting the recurrence-free survival of patients in the multivariate analysis." (PMID 32221080, 2020).